SYT7 (synaptotagmin 7)
Diseases named in the same sentence as SYT7 in open-access papers (continued):
Sharing a sentence is not in itself a finding about the gene and the disease.
osteosarcoma (2 papers, 2022 to 2024). A usually aggressive malignant bone-forming mesenchymal neoplasm, predominantly affecting adolescents and young adults. "Functional assays showed that SYT7 silencing could significantly suppress cell proliferation as well as the colony-forming ability of osteosarcoma in vitro with time independence." (PMID 36004367, 2022).
Anxiety (1 paper, 2024). Intense feelings of nervousness, tension, or panic often arise in response to interpersonal stresses. "Specifically, syt7 is expressed in auditory hair cells and the retina and moreover, syt7 knockout mice exhibit changes in auditory pre-pulse inhibition and anxiety-like behaviors, suggesting a potential role for syt7 in acoustically and/or visually-evoked behaviors." (PMID 38498506, 2024).
Arrhythmia (1 paper, 2026). Any cardiac rhythm other than the normal sinus rhythm. "Furthermore, electrocardiograms revealed that WT mice exposed to CORT developed T-wave alternans and arrhythmias, which was ameliorated by knockout of Syt7." (PMID 41424848, 2026).
bipolar I disorder (1 paper, 2025). A bipolar disorder that is characterized by at least one manic or mixed episode. "Here, we show that bipolar I disorder (BDI)-patient-induced pluripotent stem cell (iPSC)-derived islet-like organoids exhibited Syt7-dependent insulin secretion defects; moreover, Syt7-deficiency-induced insulin hyposecretion generated depression-like behaviors in Syt7 KO mice in the light phase." (PMID 40330888, 2025).
breast carcinoma (1 paper, 2021). "However, the role of THSD4 and SYT7, currently unidentified, may enhance tumor growth in a variety of cancers, especially breast cancer." (PMID 33910530, 2021). "However, the function of THSD4 and SYT7, currently unidentified, may boost tumor growth in breast cancer." (PMID 33910530, 2021).
cardiac interstitial fibrosis (1 paper, 2026). "Furthermore, knockout of Syt7 mitigated cardiac interstitial fibrosis induced by CORT, demonstrated by Sirius red staining as well as Masson's trichrome staining." (PMID 41424848, 2026). "Histological analysis further demonstrated that Syt7 knockdown mitigated CORT-induced myocardial injury including increased heart volume, increased cardiomyocyte size, cytoplasmic vacuolization, and cardiac interstitial fibrosis." (PMID 41424848, 2026).
colorectal tumor (1 paper, 2024). "Of note, rs56148061 at 11q12 was associated with differential expression of SYT7 in eQTL analysis using colorectal tumor samples (p = 0.007)." (PMID 38664626, 2024).
dysferlinopathy (1 paper, 2021). "Recently, halofuginone have been shown to directly affect myoblast fusion in the mouse models for DMD and dysferlinopathy and improve membrane repair in dysferlinopathy, probably via synaptotagmin-7 compensation." (PMID 34209117, 2021).
Glucose intolerance (1 paper, 2010). Glucose intolerance (GI) can be defined as dysglycemia that comprises both prediabetes and diabetes. "Deletion of synaptotagmin-7, a calcium sensor in insulin secretion, resulted in glucose intolerance and impaired insulin secretion in synaptotagmin-7 KO mice, even though the KO mice exhibited normal resting and fed glucose levels." (PMID 21085706, 2010).
hearing loss (1 paper, 2024). "Although differentially expressed genes associated with hormone transport are expressed in SGNs, including Slc7a5 and Syt7 as well as Spp1, their link to hidden hearing loss is less clear." (PMID 39049179, 2024).
hepatocellular carcinoma (1 paper, 2022). A malignant tumor that arises from hepatocytes. "Another study showed that SYT7 was significantly overexpressed in hepatocellular carcinoma (HCC) and was closely correlated with tumor size, differentiation, vascular invasion, and lymph node metastasis." (PMID 36004367, 2022).
Hyperglycemia (1 paper, 2011). An increased concentration of glucose in the blood. "We recently showed that without dysregulated glucagon secretion, the combination of defective insulin secretion and peripheral insulin resistance was not sufficient to induce hyperglycemia in synaptotagmin-7 KO mice." (PMID 22046328, 2011). "Consistent with the notion, our recent study showed that in the absence of dysregulated glucagon secretion, the combination of defective insulin secretion and peripheral insulin resistance was not sufficient to induce hyperglycemia in synaptotagmin-7 KO mice." (PMID 22046328, 2011).
ischemic stroke (1 paper, 2022). A stroke disorder caused by obstruction of blood flow to the brain, due to thrombotic (local blood clot formation) or embolic (due to a blood clot or other material traveling from another site) event. "Each 5% higher methylation level of targets PRDM6_4, LRRC10B_1 and SYT7_1 was associated with a 64% (adjusted OR = 0.36, 95% CI: 0.30–0.43), 51% (adjusted OR = 0.49, 95% CI: 0.41–0.58) and 71% (adjusted OR = 0.29, 95% CI: 0.25–0.34) decreased risk for ischemic stroke, respectively." (PMID 35345488, 2022). "Higher methylation levels of 18 targets in AMH, C17orf82, HDAC9, IGFBP3, LRRC10B, PDE3A, PRDM6, SYT7 and TBX2 genes were associated with a lower risk of ischemic stroke." (PMID 35345488, 2022). "Methylation of AMH, C17orf82, HDAC9, IGFBP3, LRRC10B, PDE3A, PRDM6, SYT7 and TBX2 was significantly associated with ischemic stroke." (PMID 35345488, 2022). "According to the results from stage one and stage two, we confirmed that higher methylation levels of 17 targets in AMH, C17orf82, HDAC9, IGFBP3, LRRC10B, PDE3A, PRDM6, SYT7 and TBX2 genes were associated with a lower risk of ischemic stroke." (PMID 35345488, 2022). "The results showed that the mean methylation levels of AMH, C17orf82, HDAC9, IGFBP3, LRRC10B, PDE3A, PRDM6, SYT7 and TBX2 were significantly (Wilcoxon's two sample test) lower in ischemic stroke cases than in controls." (PMID 35345488, 2022).
lymph node metastasis (1 paper, 2022). "After taking the intersection with GSE101448, 13 genes (CDK5R2, SYT7, CACNA2D2, etc.)which might prevent lymph node metastasis were further selected." (PMID 36344976, 2022).
melanoma (1 paper, 2021). A malignant, usually aggressive tumor composed of atypical, neoplastic melanocytes. "The in vivo data indicated that hnRNP A2B1 was required for tumorigenesis by affecting the splicing of TPPP3, DOCK2, EIF3H, RNF128, DAPK1, and SYT7, thus suppressing apoptosis of melanoma stem cells." (PMID 33509274, 2021). "On the other hand, the hnRNP A2B1 overexpression resulted in significant upregulations of TPPP3, EIF3H, and DOCK2 and downregulations of DAPK1, RNF128, and SYT7 in melanoma stem cells." (PMID 33509274, 2021). "Our findings revealed that the hnRNP A2B1-mediated splicing triggered the upregulation of TPPP3, DOCK2, and EIF3H, and the downregulation of RNF128, DAPK1, and SYT7 in melanoma stem cells, leading to the suppression of apoptosis of cancer stem cells." (PMID 33509274, 2021). "Western blot data indicated that the hnRNP A2B1 silencing led to significant downregulations of TPPP3, EIF3H, and DOCK2 and upregulations of DAPK1, RNF128, and SYT7 in melanoma stem cells compared with the control." (PMID 33509274, 2021). "Taken together, these findings revealed that hnRNP A2B1 played a positive role in tumorigenesis of melanoma stem cells in vivo by affecting the splicing of TPPP3, DOCK2, EIF3H, RNF128, DAPK1, and SYT7, thus suppressing apoptosis of melanoma stem cells." (PMID 33509274, 2021). "In this study, the results showed that hnRNP A2B1 suppressed apoptosis of melanoma stem cells through post-transcriptional regulation of apoptosis-related DAPK1, SYT7, RNF128, EIF3H, TPPP3, and DOCK2 genes." (PMID 33509274, 2021). "Collectively, it could be concluded that hnRNP A2B1 promoted tumorigenesis of melanoma stem cells via regulating the splicing of the precursor mRNAs of TPPP3, DOCK2, EIF3H, RNF128, DAPK1, and SYT7." (PMID 33509274, 2021). "Northern blot data indicated that TPPP3, DOCK2, and EIF3H were significantly upregulated in melanoma stem cells compared with cancer non-stem cells, while RNF128, DAPK1, and SYT7 were downregulated in melanoma stem cells." (PMID 33509274, 2021).
multiple sclerosis (1 paper, 2023). A progressive autoimmune disorder affecting the central nervous system resulting in demyelination. "This miRNA targets synaptotagmin-7 (Syt7), a synapse-associated molecule, and it upregulated considerably in multiple sclerosis (MS) lesions, where Syt7 is maldistributed (accumulated in neuronal soma and decreased in axonal structures)." (PMID 37513702, 2023).
myositis (1 paper, 2015). "As two previously reported autoimmune myositis models, wt mice immunized with C protein and Syt7−/− mice, did not develop myositis in our hand, we immunized mice of Syt7−/− background with C protein because impaired muscle membrane sealing due to Syt7 deficiency facilitates myositis induction." (PMID 26417430, 2015).
Osteopenia (1 paper, 2023). Osteopenia is a term to define bone density that is not normal but also not as low as osteoporosis. "It is speculated that APOA1, FBN1, NOTCH1, SYT7 and KLF10 played key roles in regulating bone metabolic balance and in reversible osteopenia after PAOO, which might be involved in the accelerated tooth movement." (PMID 38012627, 2023). "It is speculated that APOA1, FBN1, NOTCH1, SYT7 and KLF10 play key roles in regulating bone metabolic balance and in reversible osteopenia after PAOO, which might be involved in the accelerated tooth movement." (PMID 38012627, 2023).
primary immunodeficiencies (1 paper, 2020). "Syt7 KO CTL exhibited CG fusion similar to that of wild type CTL in low [Ca2+], indicating Syt7 is not required for CG fusion and thus may not cause primary immunodeficiencies." (PMID 32547563, 2020).
squamous cell carcinoma (1 paper, 2021). A carcinoma arising from squamous epithelial cells. "SYT7 knockdown affected the proliferation, apoptosis and cell cycle of squamous cell carcinoma cells." (PMID 34930262, 2021).
stress cardiomyopathy (1 paper, 2026). "Given the lack of effective therapies for stress cardiomyopathy, targeting Syt7 may offer a new strategy for modulating stress responses in the heart." (PMID 41424848, 2026).
type 1 diabetes (1 paper, 2020). "Cells treated with molecules mimicking type 1 diabetes lost granules with synaptotagmin-7, while granules with synaptotagmin-9 were lost in cells treated with fatty acids to imitate type 2 diabetes." (PMID 33164744, 2020).
tumor (11 papers, 2021 to 2026). "Synaptotagmin-7 (Syt7), a Ca2+ sensor with high affinity, has been associated with synaptic transmission and tumor progression, but its role in cardiac stress responses remains poorly defined." (PMID 41424848, 2026). "OGG1 facilitates tumor metastasis by assisting the transcription factor NF-κB in regulating the expression of SYT7." (PMID 40227353, 2025). "The results of immunohistochemistry (IHC) staining further confirmed the elevated expression of SYT7 in tumour tissues." (PMID 39235072, 2024). "Collectively, our study illuminates the significance of 8‐oxoG/OGG1/SYT7 axis‐driven EVs release in oxidative stress‐induced tumour metastasis." (PMID 39235072, 2024). "For example, exosome proteins (SYT7) can promote tumor angiogenesis and provide an adequate supply of nutrients and oxygen, thereby promoting tumor growth and metastasis." (PMID 38992695, 2024). "SYT7 is highly expressed in a variety of tumour tissues, contributing to a shortened disease‐free survival interval for patients, implicating its involvement in tumour initiation and progression." (PMID 39235072, 2024). "Ca2+- and synaptotagmin 7 (Syt7)-dependent lysosomal exocytosis has been suggested to play a crucial role in tumor progression and chemoresistance." (PMID 33419007, 2021). "In the study, the expression level of SYT7 in OSCC tumor tissues was higher than that in para-carcinoma tissues." (PMID 34930262, 2021). "In summary, our study demonstrated that ΔNp63α played a role in HNSCC as a tumor suppressor gene, and SYT7 played a significant role in cell proliferation, migration, apoptosis and cell cycle of HNSCC tumor cells under the regulation of ΔNp63α." (PMID 34930262, 2021). "As reported, TPPP3, DOCK2, and EIF3H act as oncogenes by suppressing apoptosis of cancer cells, while RNF128, DAPK1, and SYT7 function as tumor suppressors by promoting apoptosis of many types of cancer cells." (PMID 33509274, 2021). "It is possible that 8‐oxoG/OGG1 could drive tumour metastasis through induction of not only SYT7, but also SNAIL1 and TWIST1." (PMID 39235072, 2024). "Our data reveal that OGG1/SYT7 axis is important for oxidative stress‐induced tumour metastasis, which could be effectively suppressed by OGG1's DNA binding inhibitor Th5487." (PMID 39235072, 2024). "Thus, to validate the function of OGG1/SYT7 axis in tumour metastasis, we first expressed SYT7 in OGG1‐knockdown or OGG1‐knockout cells." (PMID 39235072, 2024). "Collectively, these data suggested that OGG1/SYT7 axis played a crucial role in tumour metastasis, which could be effectively suppressed by OGG1 inhibitor." (PMID 39235072, 2024). "The knockdown of SYT7 inhibited xenograft tumor growth of CLL cells in vivo." (PMID 37280656, 2023). "Consistently, the knockdown of SYT7 also inhibited xenograft tumor growth of CLL cells." (PMID 37280656, 2023). "In addition, the volume and weight of tumors in the SYT7 knockdown group were strikingly reduced than those in the control group, suggesting that SYT7 knockdown significantly suppressed tumor growth in vivo." (PMID 34930262, 2021). "Notably, the effect of OGG1 knockout on tumour metastasis can be rescued by SYT7 overexpression." (PMID 39235072, 2024). "Results showed that knockdown of SYT7 could also influence cell cycle of tumor cells." (PMID 34930262, 2021). "Furthermore, we also established a SYT7 knockdown HNSCC xenograft tumor model." (PMID 34930262, 2021). "Besides, we did not further evaluate the correlation between the expression of SYT7 in HNSCC and tumor pathological characteristics by statistical analysis." (PMID 34930262, 2021).
cancer (6 papers, 2019 to 2024). A tumor composed of atypical neoplastic, often pleomorphic cells that invade other tissues. "The data showed that OGG1‐deficiency‐suppressed cancer cell migration, invasion and proliferation were rescued by SYT7 overexpression." (PMID 39235072, 2024). "Nevertheless, the precise mechanisms underlying the biological activity of SYT7 remain to be elaborated on in these cancers." (PMID 36004367, 2022). "To delve deeper into the impact of OGG1/SYT7 axis on cancer metastasis in vivo, we first employed a zebrafish xenograft model, which allows quick analyses of cancer progression." (PMID 39235072, 2024). "Knockdown of SYT7 suppressed the proliferation of GC cells and attenuated the invasion, migration, and adhesion ability of cancer." (PMID 36004367, 2022). "In this study, the results of immunohistochemical staining revealed that the levels of SYT7 in OSCC tissues was markedly higher that than in para-carcinoma tissues." (PMID 34930262, 2021). "We observed that cell migration was significantly increased or decreased by SYT7 overexpression or knockdown, respectively, suggesting that SYT7 functions in cancer progression and could be a potential target for cancer therapy." (PMID 39235072, 2024). "In addition, SYT7 was found to inhibit the senescence of cancer cells." (PMID 30647108, 2019). "Taken together, these results suggested that hnRNP A2B1 regulated the pre-mRNA splicing of pro-apoptosis genes (DAPK1, SYT7, and RNF128) and anti-apoptosis genes (EIF3H, TPPP3, and DOCK2), thus leading to the suppression of apoptosis of cancer stem cells." (PMID 33509274, 2021).
infection (4 papers, 2008 to 2026). The state of being infected such as from the introduction of a foreign agent such as serum, vaccine, antigenic substance or organism. "Loss of Syt1 and Syt7 results in enlarged MR1 vesicles and an increased number of MR1 vesicles in close proximity to Mtb-containing vacuoles during infection." (PMID 41979188, 2026). "This interaction of Syt7 with peroxisomes increases during infection." (PMID 39695325, 2025). "Further, to validate that peroxisomes do not contain Syt7, peroxisomes were isolated after infection." (PMID 39695325, 2025). "The SYT7 (synaptotagmin VII) gene is associated with the control of cytotoxic granule fusion in lymphocytes, and mice lacking syt7 have reduced ability to clear an infection." (PMID 35976909, 2022).
hematologic malignancies (1 paper, 2026). "Beyond its neuronal functions, Syt7 mediates hormonal secretion and participates in development and progression of multiple cancers, gastric, hepatic, pulmonary, thyroid, ovarian, cervical, and hematologic malignancies 28-31, 80-83." (PMID 41424848, 2026).
SYT7 also shares sentences with these, for which no sentence is quoted: head and neck squamous cell carcinoma (2 papers); chronic lymphocytic leukemia (1); cognitive deficits (1); colitis (1); fragile X syndrome (1); glioma (1); Insulin resistance (1); Paralysis (1); polymyositis (1); Salmonella Infections (1); schizophrenia (1); type 2 diabetes (1).